EGFR (epidermal growth factor receptor)
Diseases named in the same sentence as EGFR in open-access papers (continued):
Sharing a sentence is not in itself a finding about the gene and the disease.
non-small cell lung carcinoma (continued). "The H1975 cell line is resistant to erlotinib, a tyrosine kinase inhibitor that improves the survival of patients with epidermal growth factor receptor (EGFR)-mutated non-small cell lung cancer." (PMID 36152073, 2022). "Tyrosine kinase inhibitors (TKIs) are used to treat non-small cell lung cancers (NSCLC) driven by epidermal growth factor receptor (EGFR) mutations in the tyrosine kinase domain (TKD)." (PMID 36357385, 2022). "This study investigated and compared clinical effect and adverse reaction rate of Oxitinib and Gefitinib in the treatment of non-small cell lung cancer complicated with EGFR gene mutation to provide reference for relevant clinical application." (PMID 35991226, 2022). "Here, the authors identify gene fusions that are associated with resistance to EGFR TKIs in non-small cell lung cancers, and test how these fusions impact the response to EGFR TKIs in vitro." (PMID 36153311, 2022). "Three variants in the EGFR gene were significantly enriched in patients with Non-Small Cell Lung cancer, consistent with acquired resistance to anti-EGFR treatment in this cancer type." (PMID 36497297, 2022). "A significant proportion (14–40%) of non-small cell lung cancers (NSCLC) displays activating mutations in the tyrosine kinase domain of epidermal growth factor receptor (EGFR)." (PMID 35840561, 2022). "Detection of point mutational biomarkers from cfDNA with ddPCR is common practice and becoming part of clinical management, for example, testing EGFR mutations in non-small cell lung cancer." (PMID 35011998, 2022). "Although epidermal growth factor (EGFR)-tyrosine kinase inhibitors (TKIs) have significantly improved the prognosis of advanced non-small cell lung cancer (NSCLC) patients with EGFR mutations, patients often develop resistance to these drugs." (PMID 35655775, 2022). "Detection of alterations in EGFR genes related to TKI treatment in EGFR-mutated non-small cell lung cancer patients is a routine method in pathology laboratories." (PMID 35884384, 2022). "15–40% of non-small cell lung cancer (NSCLC) patients harbor epidermal growth factor receptor (EGFR)-sensitizing mutations." (PMID 35482671, 2022). "The findings show that ddPCR is an accurate and rapid method for detecting EGFR mutations in patients with non-small cell lung cancer." (PMID 35202431, 2022). "The goal of current study is to explore the most appropriate radiomics modeling method to predict the progression-free survival of EGFR-TKI treatment in advanced non-small cell lung cancer with EGFR mutations." (PMID 35422007, 2022). "In RELAY, ramucirumab plus erlotinib (RAM + ERL) improved progression-free survival (PFS) in patients with untreated, metastatic, EGFR-mutated, non-small cell lung cancer (NSCLC)." (PMID 35841410, 2022). "For patients exhibiting non-small-cell lung cancer (NSCLC) with activating epidermal growth factor receptor (EGFR) mutations, epidermal growth factor receptor tyrosine kinase inhibitors (EGFR-TKIs) are a first-line treatment." (PMID 36362025, 2022). "Survival benefits and clinical responsiveness have been exhibited by various generations of EGFR-tyrosine kinase inhibitors (TKIs) in numerous randomized-controlled trials for EGFR-mutated advanced non-small-cell lung cancer (NSCLC) over the past two decades." (PMID 35884423, 2022). "In this case example, analysis was extended to a bispecific antibody (BsAb), amivantamab, which is approved for the treatment of patients with non-small cell lung cancer (NSCLC) with EGFR exon 20 insertion mutations." (PMID 35754500, 2022). "The clinical effect of oxitinib in the treatment of non-small cell lung cancer complicated with EGFR gene mutation is similar to that of Gefitinib." (PMID 35991226, 2022). "EGFR-tyrosine kinase inhibitors (EGFR-TKIs) are an important treatment option for non-small cell lung cancer patients with sensitive EGFR mutations." (PMID 36407660, 2022).
non-small cell lung carcinoma (continued). "Osimertinib is a third-generation epidermal growth factor receptor tyrosine kinase inhibitor (EGFR-TKI) designed to overcome acquired T790M resistance mutations in non-small cell lung cancer (NSCLC)." (PMID 36291877, 2022). "Osimertinib is authorized for the treatment of advanced non-small cell lung cancer as first-line treatment for patients with activating epidermal growth factor receptor (EGFR) mutations or for patients with EGFR T790M mutations." (PMID 34841493, 2022). "The EGFR exon 19 in-frame deletions are another type of activating mutation in the kinase domain that is often seen in non-small-cell lung cancer (NSCLC)." (PMID 35769445, 2022). "The OPEN/TORG2040 study is a multicenter, single-arm, phase II trial for patients with unresectable, advanced EGFR mutation-positive non-small cell lung cancer with a poor performance status (≥ 2)." (PMID 36522630, 2022). "Osimertinib is a third-generation EGFR tyrosine kinase inhibitor and the standard of care therapy for non-small cell lung cancer patients harboring EGFR-activating mutations." (PMID 35884490, 2022). "Activating EGFR mutations occur in 10–20% of patients with non-small-cell lung cancer (NSCLC) in North America and Europe and up to 60% in Asia." (PMID 35365136, 2022). "According to a study of non-small cell lung cancer, treatment with EGFR tyrosine kinase inhibitors increased tumour mutation burden and decreased CD8+ TIL densities." (PMID 35365704, 2022). "Similar to our findings, one literature found that glycolysis inhibition sensitizes non-small cell lung cancer with T790M mutation to irreversible EGFR inhibitors." (PMID 35915188, 2022). "Recent studies have shown that CUR can not only directly kill tumor cells but also enhance tyrosine kinase inhibitors (TKIs) and carboplatin against EGFR-mutated non-small-cell lung cancer." (PMID 35979255, 2022). "Tyrosine kinase inhibitors are validated therapeutic agents against EGFR-mutated non-small cell lung cancer (NSCLC)." (PMID 36080307, 2022). "Studies have revealed that non-small cell lung cancer (NSCLC) with epidermal growth factor receptor (EGFR) mutations has a high incidence of brain metastases (BMs)." (PMID 36457515, 2022). "For example, detected by Cobas EGFR mutation test v2, a digital PCR assay approved by FDA, non-small-cell lung cancer patients with EGFR exon 19 deletion or exon 21 L858R mutation can be treated by EGFR tyrosine kinase inhibitor erlotinib." (PMID 36302755, 2022). "Brain metastasis is a factor of a poor prognosis in patients with non-small-cell lung cancer (NSCLC) harboring epidermal growth factor receptor (EGFR) mutations." (PMID 36612183, 2022). "Non-small cell lung cancer (NSCLC) patients with atypical EGFR mutations have limited therapeutic options." (PMID 36615035, 2022). "Overcoming erlotinib resistance is crucial to improve the survival of advanced non-small cell lung cancer (NSCLC) patients with sensitive EGFR mutations." (PMID 35915188, 2022). "EGFR is frequently mutated and overexpressed in various cancer cells, especially non-small cell lung cancer." (PMID 35634336, 2022). "Epidermal growth factor receptor tyrosine kinase inhibitors (EGFR-TKIs) are the standard treatment for EGFR mutation-positive (EGFRm+) non-small cell lung cancer (NSCLC)." (PMID 35205720, 2022). "Somatic mutations in SMARCA4 and/or BRG1 (Brahma-related gene 1) loss are present in a subset of non-small cell lung carcinomas with distinct morphological features, harboring less EGFR mutations, but more KRAS, STK11, and KEAP1 mutations." (PMID 36371186, 2022). "Only a few studies have reported the occurrence of heart failure following the administration of osimertinib, a third-generation epidermal growth factor receptor (EGFR)-tyrosine kinase inhibitor for EGFR mutation-positive advanced non-small cell lung cancer." (PMID 35208635, 2022).
non-small cell lung carcinoma (continued). "Treatment of advanced non-small cell lung cancer (NSCLC) patients with epidermal growth factor receptor (EGFR) mutation with EGFR-tyrosine kinase inhibitors (EGFR-TKIs) can achieve good disease control, but it will inevitably produce drug resistance." (PMID 36419397, 2022). "Resistance to tyrosine kinase inhibitors in patients with EGFR-mutated non-small cell lung cancer is crucial in the development of the disease." (PMID 35884384, 2022). "Oncogenic mutations in epidermal growth factor receptor (EGFR) are used as predictive biomarkers for using EGFR TKI as a treatment strategy for non-small cell lung cancer (NSCLC)." (PMID 36153486, 2022). "Uncommon epidermal growth factor receptor (EGFR) mutations are increasingly being identified in non-small cell lung cancer." (PMID 36042660, 2022). "EGFR tyrosine kinase inhibitors (EGFR-TKIs) have revolutionized the treatment of non-small cell lung cancer (NSCLC) patients with activating EGFR mutations." (PMID 35626421, 2022). "For these reasons, we decided to investigate the role of exosomes from non-small cell lung cancer patients, particularly focusing on exosomes from EGFR-mutated patients." (PMID 35954442, 2022). "The liquid biopsy performed at the time of immunohistochemical non-small cell lung cancer diagnosis revealed within 7 days the presence of an epidermal growth factor receptor (EGFR) DEL19 activating mutation with 736,400 DNA copies/ml of plasma." (PMID 36591516, 2022). "A case of pulmonary cryptococcosis in a patient treated with erlotinib + ramucirumab for epidermal growth factor receptor (EGFR) L858R point mutation-positive non-small cell lung cancer is presented." (PMID 36450693, 2022). "About 50% of Asian non-small cell lung cancer (NSCLC) patients have sensitive epidermal growth factor receptor (EGFR) mutations." (PMID 35305596, 2022). "Epidermal growth factor receptor (EGFR)-activating mutations are the most common driver mutations in non-small cell lung cancer (NSCLC)." (PMID 35919239, 2022). "Recent publications about the new type of molecular probe of PET/CT in use for the detection of epidermal growth factor receptor mutation status in non-small cell lung cancer." (PMID 36276079, 2022). "Activating epidermal growth factor receptor (EGFR) mutations are observed in approximately 10–15% of Caucasian patients and 30–35% of Asian patients with non-small cell lung cancer (NSCLC)." (PMID 35626123, 2022). "Clinical characteristics of 53 non-small cell lung cancer–leptomeningeal metastases (LM) patients with EGFR mutation." (PMID 35978803, 2022). "This mini-review presents the mechanisms underlying the variations in patient responses, discusses the use of osimertinib against non-small-cell lung carcinomas with uncommon EGFR mutations, and addresses the future prospects of osimertinib-centered therapy." (PMID 35494059, 2022). "Epidermal growth factor receptor (EGFR) mutations are well-established oncogenic targets for management of advanced-stage non-small-cell lung cancer (NSCLC)." (PMID 34652430, 2022). "The follow-up treatment of patients with advanced non-small cell lung cancer (NSCLC) with epidermal growth factor receptor (EGFR) mutation after drug resistance to EGFR-tyrosine kinase inhibitors (TKIs) have become a hotspot and difficulty at present." (PMID 36002197, 2022). "This prospective, multicenter, observational study included 30 patients with non-small cell lung cancer treated with afatinib, harboring a major EGFR mutation confirmed by tumor tissue biopsy." (PMID 36192767, 2022). "In a previous phase I study, objective response was observed in four non-small-cell lung cancer patients with epidermal growth factor receptor mutation, and the DoR range was 5.6 to 15.7 + months when oleclumab was administered in combination with durvalumab." (PMID 36342599, 2022).
non-small cell lung carcinoma (continued). "Tyrosine kinase inhibitors (TKIs) targeting epidermal growth factor receptor (EGFR) have revolutionized the treatment landscape of the non-small cell lung cancers (NSCLCs) which harbor EGFR sensitizing mutations over the past decades." (PMID 36140210, 2022). "Erlotinib, the first FDA-approved EGFR-TKI for treating EGFR-mutated non-small cell lung cancer and pancreatic cancer, shows efficacy in some HNSCC patients." (PMID 35453686, 2022). "We designed a study that aims to investigate the efficacy and safety of first-line osimertinib treatment in patients with advanced non-small cell lung cancer harboring sensitive EGFR mutations and with poor performance status." (PMID 36522630, 2022). "Epidermal growth factor receptor (EGFR) mutations are present in about ~50.2% of non-small cell lung cancer (NSCLC)." (PMID 35372081, 2022). "Epidermal growth factor receptor (EGFR) mutations play an important role in the pathogenesis of non-small-cell lung cancer (NSCLC) and are one of the main oncogenic drivers of NSCLC." (PMID 36425553, 2022). "The European Medicines Agency and FDA have approved ctDNA-based epidermal growth factor receptor (EGFR) mutation testing for therapeutic recommendations in patients with non-small cell lung cancer (NSCLC)." (PMID 35331236, 2022). "Molecular profiling of DNA extracted from CTCs from non-small cell lung cancer (NSCLC) patients during treatment allowed monitoring of tumor evolution by mutations in the epidermal growth factor receptor (EGFR) gene related or unrelated to therapy resistance." (PMID 39697490, 2022). "Sensitizing somatic mutations of the epidermal growth factor receptor (EGFR) gene were found in about 10% of Caucasian and 50% of east Asian patients with non-small cell lung cancer (NSCLC)." (PMID 35565285, 2022). "EGFR activating mutations define a specific molecular subset of non-small cell lung cancer (NSCLC) patients." (PMID 35955661, 2022). "Epidermal growth factor receptor (EGFR) resistance to tyrosine kinase inhibitors can cause low survival rates in mutation-positive non-small cell lung cancer patients." (PMID 36555475, 2022). "EGFR mutation is the most common gene mutation among patients with non-small-cell lung cancer and occurs in 50%–60% of Asian patients; most patients with these mutations have a low survival rate." (PMID 36467503, 2022). "Leptomeningeal metastases (LM) have become increasingly common in non-small cell lung cancer (NSCLC) patients who harbor epidermal growth factor receptor (EGFR) mutation treated with EGFR-TKI and are correlated with inferior prognosis." (PMID 35978803, 2022). "HER2 is less common than EGFR, is a significant predictor of decreased overall survival in patients with breast cancer, and is associated with poor prognosis in patients with non-small cell lung cancer." (PMID 36713381, 2022). "Erlotinib (ERL) is a very lipophilic drug (clog P ~ 3.2) and potent epidermal growth factor receptor (EGFR) inhibitor (IC50 ~ 2 nM) currently marketed as tablets (Tarceva®) for the treatment of EGFR mutation-positive non-small-cell lung cancer." (PMID 35164335, 2022). "Epidermal growth factor receptor (EGFR) activation mutation has been demonstrated to be driver genes in non-small cell lung cancer (NSCLC) that can benefit from oral EGFR tyrosine kinase inhibitors." (PMID 35747829, 2022). "Epidermal growth factor receptor (EGFR) tyrosine kinase inhibitors (TKIs) have been widely used in the treatment of EGFR mutation non-small-cell lung cancer." (PMID 35365136, 2022). "These extend from systemic ICIs monotherapy to combinations with chemotherapy or targeted therapies in cases with relevant tumor mutations (e.g., BRAF/MEK in melanoma and EGFR in non-small cell lung cancer, NSCLC)." (PMID 35376991, 2022). "EGFR mutation is revealed to be related to response to the receptor antagonist drugs (such as gefitinib) in patients with non-small cell lung carcinoma (NSCLC)." (PMID 35463723, 2022).
non-small cell lung carcinoma (continued). "Phase I and III clinical trials have shown that simertinib is effective in patients with locally advanced or metastatic EGFR mutation-positive non-small-cell lung cancer." (PMID 35757653, 2022). "TTD definitions differing by reference score and deterioration event were used to analyse data from the phase 3 FLAURA trial of first-line osimertinib versus erlotinib or gefitinib in patients with EGFR-mutated advanced non-small cell lung cancer." (PMID 35099678, 2022). "Patients with non-small-cell lung cancer, especially those with lung adenocarcinoma, are prone to mutations in a variety of driver genes, including epidermal growth factor receptor (EGFR), anaplastic lymphoma kinase (ALK), and other mutations." (PMID 36304772, 2022). "Other mutations in ErbB genes observed in non-small-cell lung cancer include somatic activating mutations in EGFR tyrosine kinase domain, which slow down receptor deactivation." (PMID 35448364, 2022). "In this study, we developed a fusion model for predicting EGFR mutation levels in 1074 patients with non-small cell lung cancer by analyzing the clinical, radiology, radiomic, and deep learning features." (PMID 35186727, 2022). "In pretreatment tumor samples of EGFR-mutated non-small cell lung cancer (NSCLC) patients, EGFR-Thr790Met mutation has been detected in a variable prevalence by different ultrasensitive assays with controversial prognostic value." (PMID 35955661, 2022). "Ganetespib, a heat shock protein 90 inhibitor, used in clinical trials for the treatment of non-small cell lung carcinoma with EGFR, KRAS, or ALK mutations, was effective in all cell lines with a stronger inhibition in CRMM2." (PMID 35326726, 2022). "The development of first-, second-, and third-generation epidermal growth factor receptor–tyrosine kinase inhibitors (EGFR-TKIs) has significantly improved the clinical outcomes of advanced EGFR-mutated non-small-cell lung cancer (NSCLC) patients." (PMID 36611420, 2022). "Activating mutations in the epidermal growth factor receptor (EGFR) are key drivers of non-small-cell lung cancer (NSCLC) in 10–15% of Caucasian patients and 50% of Asian patients." (PMID 36145591, 2022). "Patients with non-small cell lung cancer harboring the epidermal growth factor receptor (EGFR)-sensitive mutations are known to benefit significantly from EGFR tyrosine kinase inhibitors (TKIs), such as erlotinib, gefitinib, icotinib, or afatinib." (PMID 35712479, 2022). "Leptomeningeal metastasis (LM) is a complication of deeper concerns due to its increasing incidence rate, limited treatment options, and dismal survival outcomes in patients with EGFR-mutated non-small cell lung cancer (NSCLC)." (PMID 35644609, 2022). "Epidermal growth factor receptor tyrosine kinase inhibitors (EGFR-TKIs) are the preferential options for advanced non-small cell lung cancer (NSCLC) patients harboring EGFR mutations." (PMID 36482474, 2022). "Epidermal growth factor receptor (EGFR) mutations are identified in approximately 32% of non-small-cell lung cancer (NSCLC) patients." (PMID 35408753, 2022). "In contrast to non-small cell lung cancer and adenocarcinoma harboring activating nucleotide mutations within the EGFR kinase domain, GBM overly activates EGFR by the increasing copy number and the substituted mutations occur in the extracellular domain." (PMID 35785151, 2022). "It has been reported that 10–15% of Caucasian patients and 30–35% of Asian patients with non-small cell lung cancer (NSCLC) harbor activating EGFR mutations." (PMID 36615035, 2022). "Recent publications about the association of 18F-FDG metabolic parameters of PET/CT with epidermal growth factor receptor mutation status in non-small cell lung cancer." (PMID 36276079, 2022). "Osimertinib resistance limits the treatment of epidermal growth factor receptor-(EGFR)-mutated non-small-cell lung carcinoma (NSCLC)." (PMID 35168607, 2022).